TNF (tumor necrosis factor)
Diseases named in the same sentence as TNF in open-access papers (continued):
Sharing a sentence is not in itself a finding about the gene and the disease.
depression (continued). "Moreover, in biochemical analysis, glycitein also reduced the brain TBARS and serum tumor necrosis factor-alpha (TNF-α) levels and the potential to manage depression and impaired memory by inhibiting lipid peroxidation and inflammatory stress." (PMID 40941056, 2025). "In 12 longitudinal studies about the relationship of blood cytokines in adolescents with major depressive disorder (MDD), their results consistently revealed that for adolescents with MDD, their peripheral blood cytokines concentrations, such as TNF-α and IL-8 were remarkably increased." (PMID 40375217, 2025). "Fifteen studies involving measurements of inflammatory proteins and level of depression in 1102 individuals with MS were included in the meta-analysis: five for interleukin (IL)-10 (LPS and PHA), four for tumour necrosis factor (TNF)-α, four for interferon (IFN)-γ, and four for IL-6 (LPS and PHA)." (PMID 39867847, 2025). "Participants in the depression group exhibited higher occipital skull SUVs [mean = 0.975, standard error of the mean (SEM) = 0.043] than controls (mean = 0.791, SEM = 0.064), after adjusting for ACC SUV and TNFα." (PMID 39657983, 2025). "Proposed mechanisms of the development of sleep disturbances include the release of cytokines such as tumor necrosis factor (TNF) or C-reactive protein (CRP), depression and distress, cancer-related fatigue, menopausal hormone therapy (MHT), chemotherapy, radiotherapy, and surgery." (PMID 41357522, 2025). "Mental health practitioners could incorporate inflammatory marker panels (e.g., IL-6, TNF-α, CRP) into assessment protocols, particularly for patients with depression subtypes characterized by elevated inflammation." (PMID 40964429, 2025). "Depression is not merely a reactive psychological state but a systemic inflammatory condition that amplifies cytokine-mediated vascular damage (e.g., IL-6, TNF-α) and dysregulates autonomic nervous system activity." (PMID 40904459, 2025). "Similarly, human studies have consistently found that circulating levels of at least 15 markers such as CRP, IL-2, IL-6, CCL3, TNF-α, and TNF-β (also known as Lymphotoxin-alpha) were increased in patients with depression." (PMID 41010394, 2025). "Paraclinical evaluation, such as reduced FEV1 and elevated CAT scores, has been identified as an aggravating factor, accompanied by laboratory findings of high inflammation factors such as IL1 beta, IFN-γ and IL-2, and TNF, would be present in patients with both COPD and depression." (PMID 41008474, 2025). "However, the majority of existing epidemiological studies have primarily examined relationships between interleukin-1b (IL-1b), interleukin-2 (IL-2), interleukin-6 (IL-6), tumor necrosis factor-alpha (TNF-a), and other inflammatory factors and depression." (PMID 40530060, 2025). "PPI network analysis identified core targets such as MAPK3, STAT3, AKT1, PRKACA, MAPK1, and TNF, suggesting BCBL's efficacy in depression treatment may stem from its action on multiple key targets." (PMID 40909251, 2025). "In addition, DHM achieves synergistic relief of pain and depression symptoms by downregulating P2X7 receptor expression, blocking the ATP-gated ion channel-mediated ERK1/2 phosphorylation cascade, and reducing TNF-α and IL-1β levels." (PMID 40740995, 2025). "Depression activates the IRS, which produces pro-inflammatory factors such as TNF-α and IL-6." (PMID 39980978, 2025). "Three studies reported significant differences in inflammatory protein concentrations between MS participants with and without depression for IL-6 in serum, and IL-9,30 TNF-α and CRP in both serum and CSF." (PMID 39867847, 2025). "In depression, pro-inflammatory cytokines such as IL-1β, IL-6 and TNF-α play a distinct role, not merely facilitating immune responses but also participating in the regulation of neurochemical, neuroendocrine and neuroplasticity processes." (PMID 40612748, 2025).
depression (continued). "Patients with depression typically exhibit elevated levels of inflammatory markers, such as C-reactive protein (CRP), tumor necrosis factor-α (TNF-α), and interleukin-6 (IL-6), which can impact the functioning of the central nervous system, causing mood disorders and cognitive decline." (PMID 40313907, 2025). "Study has suggested that individuals with depression generally display higher levels of interleukin-1 (IL-1), IL-6, TNF-α, and CRP compared to non-depressed individuals." (PMID 40313907, 2025). "Subsequently, the downstream signal transduction pathways were activated and large amounts of inflammatory mediators were released, such as TNF-α, which cross the blood-brain barrier (BBB) to induce dysregulation of neurotransmitters and promote depression-like behaviors." (PMID 41179813, 2025). "Isorhamnetin improved pain–depression phenotypes and cognitive function, while increasing glutathione (GSH) and lowering TBARS and pro-inflammatory cytokines (TNF-α and IL-1β), as well as rebalancing neurotransmitters by decreasing glutamate and increasing serotonin and norepinephrine)." (PMID 41470214, 2025). "Notably, IL-6 and TNF-α are potent modulators of both serotonin metabolism and hypothalamic-pituitary-adrenal (HPA) axis activity, providing a plausible link to anxiety/depression scores in our cohort." (PMID 41282285, 2025). "Elevated expression of tumor necrosis factor-α (TNF-α), interleukin-1β (IL-1β), interleukin-6 (IL-6), and nuclear factor kappa B (NF-κB) signaling have been identified in patients with depression and replicated in animal models of high-fat diet (HFD) and stress-induced behavioral despair." (PMID 40558565, 2025). "A meta-analysis of 107 studies in the general adult population found that individuals with depression had elevated C-reactive protein (CRP), interleukin (IL)-3, IL-6, IL-12, IL-18, soluble interleukin 2 receptor (sIL-2R), and tumor necrosis factor alpha (TNF-α) levels with medium-effect sizes." (PMID 39902492, 2025). "Another probiotic mixture containing L. lactis, L. cremoris, L. diacetylactis, L. acidophilus, and lactic yeasts also confers protection against LPS-induced depression and anxiety in CD1 mice by reducing the serum levels of IL-12, TNF-α, IL-1β, and TNF-α in the brain." (PMID 40804450, 2025). "Interestingly, in the combined sample, IL‐18, TNF‐α, and the proinflammatory PC‐1 values positively correlated with measures of AUD severity and anxiety/depression measures." (PMID 40317574, 2025). "Depression, IPF, frailty and peripheral inflammation at baseline and after follow-up were evaluated by indicators and scales such as BDI-II, FVC %pred, 6MWT, mMRC, CFS, TFI, SGRQ, K-BILD, IL-6, and TNF-α." (PMID 40120048, 2025). "Furthermore, individuals with depression often exhibit elevated levels of CRP and TNF in their blood." (PMID 40852367, 2025). "In a diabetic neuropathy model with comorbid depression, DHM alleviated both neuralgia and depressive symptoms by suppressing P2X7 receptor expression, thereby reducing ERK1/2 phosphorylation and proinflammatory cytokines (TNF-α, IL-1β)." (PMID 40740995, 2025). "In our review, we noticed that TNF-α decreased with the administration of the SSRI escitalopram (two studies, moderate depression and MDD) and ketamine (two different studies on treatment-resistant depression)." (PMID 40573262, 2025). "Depression and Alzheimer’s disease have comparable pathophysiological processes, such as impaired BDNF, compromised transforming-growth-factor-β1 (TGF-β1) signaling, and abnormal TNF-α signaling." (PMID 39459643, 2024). "Interestingly, TNF-α levels showed positive correlation with Hospital Anxiety and Depression Scale-Anxiety (HADSA) and Hospital Anxiety and Depression Scale–Depression (HADSD)." (PMID 38362105, 2024). "Additionally, other studies have reported an association between elevated levels of tumor necrosis factor-alpha (TNF-α) and monocyte chemotactic protein-1 (MCP-1) and depression." (PMID 38809848, 2024).
depression (continued). "While there is also report shows that suicidal adolescents with depression have lower plasma TNF-α levels than non-suicidal one." (PMID 38459460, 2024). "From the increased levels of proinflammatory cytokines, such as interleukin-6 (IL-6) and tumor necrosis factor-alpha (TNF-α), measured in individuals diagnosed with depression, to the PET scan visualization of neuroinflammation in individuals experiencing depressive episodes." (PMID 38645426, 2024). "Meanwhile, individuals who had increased level of both pro-inflammatory cytokine tumor necrosis factor-alpha (TNF-α) and interleukin 8 (IL-8) have been reported to develop psychiatric disorders such as major depression, bipolar disorder, schizophrenia and sleep disorder." (PMID 38362105, 2024). "Another link between depression, cognitive disorders, and CHF seems to be related to alterations of neurohormone levels such as cortisol or to the presence of pro-inflammatory cytokines (IL-6, TNF-α, C-reactive protein)." (PMID 39597044, 2024). "In the first study of 31 people with AD and depression, 24 with AD and no depression, and 37 age-matched controls, peripheral IL6 and TNF were elevated in those with AD and depression compared to both those with AD and no depression and controls." (PMID 38175420, 2024). "While many studies have reported increased levels of TNF-α in individuals with depression, it is essential to acknowledge that not all studies have consistently produced these positive findings." (PMID 39273641, 2024). "In PD patients with depression, TNF-α level in CSF was significantly higher than those without depression." (PMID 38755545, 2024). "In our study we found an increase in TNF-α in the anterior insula in AD with depression, but not in the superior frontal gyrus." (PMID 39526037, 2024). "Our study may therefore provide additional explanations of how TNF-α exacerbates depression, suggesting that regulating levels of TNF may decrease depression." (PMID 38710713, 2024). "It is proposed that inflammation is a key for depression, with approximately one-third of adults with depression exhibiting elevated levels of inflammatory cytokines, including C-reactive protein (CRP), tumor necrosis factor α (TNF-α), and interleukin-6 (IL-6)." (PMID 40226688, 2024). "Patients with bipolar disorder were more likely to have an increased TNF-α level and perform worse in the go/no-go task compared with those with major depressive disorder." (PMID 39283831, 2024). "In recent years, a series of studies have noted that biological indicators in peripheral blood samples, mainly IL-1, IL-6, TNF-α, IFN-α, C-reactive protein, neurotrophic factor and KYN pathway metabolites, can be analysed as criteria for the diagnosis of depression." (PMID 39654767, 2024). "A meta-analysis examining cytokine levels in individuals with major depression found that depressed subjects had significantly elevated serum levels of TNF-α and IL-6 compared to non-depressed controls." (PMID 39682736, 2024). "Indeed, recent meta-analyses have reported higher levels of TNF-α, CRP, and IL-6 levels in adolescents with depressive disorders when compared with control individuals." (PMID 38824135, 2024). "Higher levels of pro-inflammatory markers such as CRP, IL-6 and TNF-α and more fatigue are seen in patients with depressive disorders because of negative effects on the nervous system." (PMID 38297218, 2024). "Depression-like behavior was measured by a series of behavioral tests and neurobiochemical factors (5-HT, DA, and BDNF) and pro-inflammatory factors (IL-6 and TNF-α) were measured in brain tissues, combined with Nissl pathological analysis and determination of gut microorganisms." (PMID 37692389, 2023). "It has also been observed that TNF-a activates the hypothalamic-pituitary-adrenal (HPA) axis, which leads to the depletion of tryptophane and the subsequent decrease in serotonin (5-HT) levels and the onset of depression." (PMID 37240864, 2023).
depression (continued). "IL-6, TNF-α and IFN-γ were associated with depression and suspiciousness, but not to other positive or negative symptoms, while controlling for all other symptoms in the network." (PMID 37723153, 2023). "Studies have reported that IL-6, TNF-α, CRP, YKL-40, IL-17, IL-1β, CCL2, IL-2, and IL‐8 are related to worse cognitive function or cognitive deterioration, while CRP, TNF-α, sIL-2R and CCL2 reflect severe symptoms of depression and anxiety." (PMID 36739284, 2023). "Notably, ZSQGY was able to reduce the levels of IL-1β, IL-6, TNF-α, and IFN-γ, which demonstrated the anti-inflammatory effects of ZSQGY in the central nervous system in the MSG-induced depression model." (PMID 37251232, 2023). "The mechanism may be that exercise can inhibit the neuroinflammatory response in the NF-κB and TNF-α/IDO/5-HT signaling pathway and then improve depression." (PMID 37239191, 2023). "Two clinical trials of the TNF-α inhibitor infliximab in depression showed no overall significant efficacy." (PMID 37181897, 2023). "In the pain-depression dyad model, the AFIC-CDs groups decreased the immobile time, showed effect in increasing both the neurotransmitters’ levels and the expression of mRNA of BDNF and Tph2, and decreased the IL-1β and TNF-α levels in mouse brain cortex." (PMID 38259687, 2023). "Interestingly, a positive Spearman correlation was maintained at the mRNA level in PBMCs of depression patients, between CCL2, IL-6 and TNF-α." (PMID 37575572, 2023). "In humans, the levels of pro-inflammatory cytokines IL-1β, IL-6, and TNF-α were reported to be significantly higher in the post-mortem brains of suicided patients with depression than in those of matched non-psychiatric controls." (PMID 37273278, 2023). "In a multicenter prospective study conducted in Spain, although depression, anxiety, lack of sleep, and extraintestinal manifestations were related to fatigue, disease activity and anti-TNF therapy were not related to fatigue, contrary to our results." (PMID 37176558, 2023). "There is ample evidence to support the association between increased cortisol and pro-inflammatory cytokines (IL-1β, IL-6, IL-8, TNF-α) in negative mood conditions, stress levels, anxiety, and depression." (PMID 36986501, 2023). "Spearman’s correlation analysis showed that different microbial communities (Corynebacterium, Faecalibaculum, Enterorhabdus, Desulfovibrio) correlation with differential metabolites (Cholic acid, Deoxycholic acid, etc.)and depression-related biochemical indicators (5-HT, DA, BDNF, IL-6, and TNF-α)." (PMID 37692389, 2023). "A total sample of 60 community-dwelling older adults with chronic low back pain (cLBP) provided blood samples for high-sensitivity TNF-α and completed the Gratitude Questionnaire, Perceived Stress Scale, and the PROMIS Emotional Support, Sleep Disturbance, and Depression forms." (PMID 37213708, 2023). "IL-6 and its downstream impact on TNF-α, and IFN-γ, could offer novel targets for treatment if offered at the relevant phenotypic profile including those with depression." (PMID 37723153, 2023). "Tumor necrosis factor α (TNF-α) and Interleukin 6 (IL-6) can attach to their receptors and trigger cerebral Nuclear factor kappa B (NF-kB) signaling, which can upregulate the production of secondary cytokines, and finally induce depression symptoms." (PMID 37386551, 2023). "Plasma concentrations of stress and inflammatory biomarkers (cortisol, CRP, IL-6 and TNF-α) have been found to be increased in patients with major depressive disorder who have a history of treatment non-response, compared to treatment-responsive patients." (PMID 36648973, 2023). "Patients with depression tend to demonstrate significantly elevated levels of various chemokines (CCL2, CXCL10), and pro-inflammatory cytokines, such as interleukin (IL)−1β, IL-6, and tumor necrosis factor (TNF)." (PMID 36978923, 2023).
depression (continued). "In rodent models of depression, these drugs may also reduce inflammation and proinflammatory cytokines IFN-γ, IL-6 and TNF-α." (PMID 37298431, 2023). "In addition, the results revealed that compared with the control group, the levels of TNF‐α and IL‐1β were significantly increased in CUMS‐induced depression‐like mice." (PMID 37408379, 2023). "Major depressive disorder (MDD) patients showed abnormal circulating CD4+ T lymphocytes with expansion of the IL-17 and TNF-alpha expressing cells as well as increased levels of peripheral IL-17 and TNF-alpha." (PMID 38067176, 2023). "Cancer patients showed increased levels of proinflammatory cytokines (IFN-γ, TNF-α, and IL-6) and oxidative stress markers (MDA and CC levels), which were further significantly enhanced in cancer patients with depression compared to normal healthy (NH) individuals." (PMID 37153524, 2023). "Phase-I multiple regression analyses showed that young children exposed to high levels of socioeconomic disadvantage had higher salivary levels of TNF-α, IL-1β, and hair DHEA after adjusting for family dysfunction, caregivers’ depression, and anxiety levels (respectively)." (PMID 36650307, 2023). "For instance, TNF‐α, IL‐1β, IL‐6, and IL‐17A are elevated in coronary heart disease patients with anxiety and depression in comparison to those without these disorders." (PMID 37878890, 2023). "Moreover, a recent study revealed that the serum level of sIL-6R, but not IL-6 or TNF-α, is significantly associated with the pathogenesis of the treatment-resistant major depressive disorder, suggesting that IL-6 trans-signaling may be involved in the onset of this disease." (PMID 37187893, 2023). "Pentoxifylline, a methylxanthine drug that acts as a strong non-selective TNF-α inhibitor, has improved depressive behavior in animal models but has also shown positive results as an add-on treatment for depression." (PMID 36899845, 2023). "Higher levels of TNF-α and IL-6 in patients with BPD and depression (P<0.05)." (PMID 36946840, 2023). "Recently, it was shown that the treatment with the probiotic Bacillus coagulans Unique IS-2® reduced chronic stress-induced depression in rats by a mechanism related to an increase in BDNF and 5-HT levels and a decrease in TNF-α, IL-1β, and dopamine levels in the hippocampus and frontal cortex." (PMID 37892186, 2023). "While it is clear that TNF-α signalling in specific brain regions mediates diverse behavioural responses, future studies are likely to refine existing knowledge of the role of TNF signalling with regard to specific depression symptoms." (PMID 37457896, 2023). "Higher levels of TNF-α and IL-6 in patients with BPD and current depression (P<0.05)." (PMID 36946840, 2023). "Several reports indicated that patients with depressive disorders have higher levels of pro-inflammatory cytokines, such as C-reactive protein (CRP), interleukin (IL)-1, (IL)-6, and tumor necrosis factor-alpha (TNF-alpha) in their plasma than healthy individuals." (PMID 37916205, 2023). "Depression was a strong negative predictor of disease remission in patients with RA after 3 and 6 months of anti-TNF or MTX treatment." (PMID 36755665, 2022). "However, in general, it is known that pro-inflammatory cytokines are increased in major depressive disorder (MDD), with the most remarkable increases in IL-6, TNF, and C-reactive protein (CRP)." (PMID 35884835, 2022). "COX-2 overexpression leads to an increase in the pro-inflammatory cytokines IL-1β, IL-6 and TNF, which increases the activity of the 5-HT transporter protein SERT, increases the affinity of the 5-HT receptor 5-HT1A, and mediates depression through an IDO mechanism that alters tryptophan metabolism." (PMID 36440427, 2022). "A previous study with monoclonal antibody against TNF-α revealed that this intervention quelled symptoms of anhedonia but did not affect depression scores significantly compared to placebo groups." (PMID 35782423, 2022).